IL22 (interleukin 22)
Diseases named in the same sentence as IL22 in open-access papers (continued):
Sharing a sentence is not in itself a finding about the gene and the disease.
colitis (continued). "Additionally, BCFAs and SCFAs generated by C. sporogenes enhanced the activity of Tregs and increased the production of IL-22, which led to protection from colitis." (PMID 39397690, 2024). "The authors suggested that IL‐22 may facilitate colitis pathology by recruiting neutrophils to the site of intestinal damage." (PMID 38363052, 2024). "Conversely, several reports indicate that IL-22 can exacerbate colitis." (PMID 39379604, 2024). "In line with this, AHR-deficient mice exhibit a marked reduction in the number of ILC22 and the secretion of IL-22 and are unable to mount a protective response during Citrobacter Rodentium infection, a mouse model that mimics human colitis induced by attaching and effacing enterotoxigenic E. coli." (PMID 38674118, 2024). "IL-22 strengthens the intestinal barrier and has been shown to alleviate colitis in mice models." (PMID 37512497, 2023). "Besides its beneficial role, studies however indicate that overexpression of IL-22 results in high antimicrobial peptides production with loss of bacterial diversity in IL10-/- mice, which develop spontaneous colitis compared to IL10-/-IL-22-/- mice." (PMID 37849749, 2023). "Then we administered B. fragilis orally in a DSS-induced colitis IL-22-/- mice model." (PMID 37114045, 2023). "Thus, using IL-22 fusion proteins to improve IL-22 function appears to be a therapeutic strategy that is effective in the DSS-induced mouse model of colitis." (PMID 37122757, 2023). "Therefore, we investigate if AhR orchestrates the effects of combined butyrate and VD3 on cytokines response (IL-17A and IL-22), antimicrobial peptides (LL-37), and tight junction proteins expression to block the invasion of Salmonella in colitis mice." (PMID 36678175, 2023). "The protective effects of IL-22 in colitis were dependent on epithelial STAT3 activation." (PMID 37432218, 2023). "Similarly, I3A, an indole derivative that is produced via tryptophan metabolism by Lactobacilli, restores IL-22 production and ameliorates colitis when administered to colitis induced mice." (PMID 37835602, 2023). "Furthermore, animal studies have reported that AhR deficiency aggravates inflammation in T cell transfer- and DSS-induced mice colitis and that it induces colitis by reducing IL-22 release." (PMID 37554552, 2023). "Indole derivatives confer protection in murine models of colitis, largely via AhR activation, leading to increased IL-22 production by ILC3s and T cells that drives improved intestinal barrier integrity, reduced inflammation, and, ultimately, disease amelioration." (PMID 36894983, 2023). "Moreover, it has been shown that a soluble antagonist of IL-22 binding protein (IL-22BP) was elevated during IBD, which can block the protective biological effects of IL-22 in colitis, particularly mucosal healing." (PMID 37122757, 2023). "In addition, using a cre-flox system to delete Odc1 in Rorc-expressing cells, they found that ODC had a role in in vivo IL-22 production by ILC3s during two distinct models of colitis." (PMID 36637514, 2023). "To verify the assumption, we administered B. fragilis to mice in a DSS-induced colitis mouse model and found that B. fragilis facilitates colonic mucosa proliferation, and mucus secretion, and alters gut microbiota in colitis via motivating the STAT3 pathway induced by IL-22 from ILC3 secretion." (PMID 37114045, 2023). "It suggests that B. fragilis promotes ILC3 cells to secrete IL-22 in DSS-induced colitis." (PMID 37114045, 2023). "Products of microbial metabolism can activate AhR and upregulate IL-22 production, leading to increased AMP and mucin production in IECs which in turn contribute to reduced colitis susceptibility and may shape microbiome composition and function." (PMID 36894983, 2023). "In addition, microbial tryptophan metabolites signal through AhR to increase IL-22 secretion by innate-like lymphoid cells and T cells, leading to protection from chemically induced colitis." (PMID 37072819, 2023).
colitis (continued). "In addition, acetic acid can restore the decreased expression of MUC2 proteins in colonic crypts and repair the damaged mucus barrier, and butyric acid can alleviate colitis through enhancing IL-22 production." (PMID 37111225, 2023). "However, ILC3s — which produce IL-22 — can also lead to the development of acute congenital colitis in mice." (PMID 37304260, 2023). "FICZ, a tryptophan photoproduct, can alleviate both DSS-induced enterocolitis and trinitrobenzene sulfonic acid or T-cell transfer-induced colitis by reducing the production of proinflammatory cytokines and increasing the production of anti-inflammatory IL-22 by Th17 cells." (PMID 37179416, 2023). "Of note, we have observed a discrepancy in genetic and pharmacological TNF inhibition on IL-22BP production: blockade of T cell-derived TNF during established colitis induced tissue repair via the IL-22/IL-22BP axis, while genetic depletion of TNF in T cells did not affect IL-22BP." (PMID 35383266, 2022). "Therefore, there is an urgent need to explore the features of lncRNAs on the intestinal epithelium in colitis under the effect of IL-22." (PMID 36092152, 2022). "The mRNA level of Il-22, an important anti-inflammatory cytokine, was decreased in colitis mice." (PMID 35889745, 2022). "Notably, evidence in colitis models also showed a protective effect of IL-22, which reflects the complex function of IL-22 related to intestinal inflammation." (PMID 36135048, 2022). "Several research works supported that IL-10 is highly relevant to IBD, and IL-10−/− mice would spontaneously develop colitis, which may be related to the production of IL-22." (PMID 36176442, 2022). "GSTT1 is found to alleviate colitis by the IL-22 dependent pathway." (PMID 35893911, 2022). "Ginger derived EVs can also rely on the mechanism of IL-22 production to improve colitis in mice." (PMID 35745626, 2022). "IL-22 enhances the defense ability of the barrier and alleviates the symptoms of colitis." (PMID 35745626, 2022). "Next, we investigated whether IL-22-mediated regulation of neutrophil-active chemokine expression was functionally important in colitis." (PMID 36192482, 2022). "Moreover, the reparative cytokine IL-22 was confirmed to drive repair in the intestinal epithelium through decreasing inflammation response in the colitis model." (PMID 36466900, 2022). "Observation from the earlier study prompted increased CD4+ cell population, and IL22 cytokine expression in colitis patients was tightly correlated with upregulation of carbohydrate and nucleotide metabolism and downregulation of amino acid and lipid metabolism." (PMID 35263357, 2022). "We investigated whether IL-22 responsive transcripts were enriched in the colon in mouse models of colitis." (PMID 36192482, 2022). "To directly address whether IL-22 drives colonic epithelial cell proliferation and subsequent repair during colitis in vivo, we concomitantly neutralized IL-22 by blocking antibodies together with anti-TNF treatment." (PMID 35383266, 2022). "After observing aberrant p-STAT3 staining in colonic epithelial cells of TAM-treated Klf5ΔIND mice and DOX-treated C2BBEΔIND cells after IL-22 stimulation, we next investigated whether such a phenomenon is present in patients with colitis." (PMID 35393949, 2022). "The plant-derived indole, I3C, has been shown to bind to the aromatic hydrocarbon receptor (AhR) found in most tissues, including the gut where it decreases colitis by reducing microbial dysbiosis and boosting the abundance of butyrate-producing Gram-positive bacteria in an IL-22–dependent way." (PMID 35631553, 2022). "Interestingly, IL-21 signalling was recently proposed to dampen T-cell transfer colitis by reducing IL-17A production and augmenting IL-22 production in populations of ILC3s." (PMID 36012618, 2022). "Accordingly, we first estimated the therapeutic effect of IL-22 on DSS-induced colitis in mice." (PMID 36092152, 2022).
colitis (continued). "We confirm that LRBA KO mice have significantly reduced expression of CTLA4 in Treg cells but also that reduced IL17 and IL22 production by ILC3 in the gut may further exacerbate DSS-induced colitis." (PMID 35603158, 2022). "Subsequently, IL-23 signalling within intestinal epithelial cells was found to play an important role in protection against DSS colitis by regulating regenerating-islet-derived protein 3-beta (Reg3β)-dependent control of flagellated intestinal bacterial abundance and promoting IL-22 production." (PMID 36012618, 2022). "In addition, B. ovatus was reported to produce indole-3-acetic acid that promoted IL-22 production by immune cells, yielding beneficial effects on colitis." (PMID 35281043, 2022). "For instance, in an adoptive transfer colitis model when Treg-depleted memory/effector CD4+CD45RBlo T cells were transferred into RAG-1-/- mice, IL-22 derived from these memory/effector T cells is pathogenic, whereas IL-22 is protective when CD4+CD45RBhi naïve T cells were transferred." (PMID 34992594, 2021). "Similarly, indigo naturalis, which has been traditionally used in Chinese medicine, turned out to mediate its protective effect via AhR-mediated IL-22 production in ILC3s as well, resulting in reduced disease severity in several murine models of colitis." (PMID 33869257, 2021). "Next, to test whether suppression of colitis by iNKT cells correlates with IL22-producing ILC3s in Yeti mice, we performed adoptive transfer experiments to investigate the cooperative relationship between iNKT cells and ILC3s in colitis suppression." (PMID 33513946, 2021). "Tregs prevent ILC3-associated colitis by inhibiting IL-23 and IL-1β production from intestinal-resident C-X3-C Motif Chemokine Receptor 1 (CX3CR1)+ macrophages, which restrains ILC3-linked IL-22 production." (PMID 34299236, 2021). "In addition to the animal data, recent human studies also challenge the dogma of IL-22 being beneficial for colitis, especially during chronic inflammation, instead of in acute, self-limiting mucosal injury." (PMID 34992594, 2021). "Reversal of colitis symptoms by antagonistic IL-22BP-Fc suggested that signaling through supraphysiological amounts of IL-22 and its receptor IL-22RA1 in the gut is detrimental, and could possibly induce colonic epithelial ER stress and consequent apoptosis." (PMID 34992594, 2021). "Development of colitis was associated with a 3- to 60-fold increase in mRNA expression levels of pro-inflammatory cytokines including IL-1β, tumor necrosis factor (TNF)-α, interferon (IFN)-γ, IL-17, and IL-22." (PMID 34299013, 2021). "Using a mouse model of Th2-mediated colitis, IL-22 gene delivery could induce expression of mucus components and goblet cells in a STAT3-dependent manner, which resulted in increased mucus production and thus less severe colitis." (PMID 33869257, 2021). "Rather than rendering the mice vulnerable to C. rodentium, mice treated with M(IL4)s showed enhanced protection against infection and less colonic histopathology that correlated with reduced mRNA expression of IL-22, IL-17 and IFNγ, hallmarks of C. rodentium-colitis." (PMID 34691050, 2021). "Amelioration of colitis symptoms in MSC-/- mice by IL-22-blocking agent IL-22BP-Fc suggests a counterintuitive pathogenic role of IL-22 in the absence of MSC as a checkpoint." (PMID 34992594, 2021). "Rheostatic regulation of IL-22 may be of therapeutic value to restore homeostatic balance and promote intestinal health in human colitis." (PMID 34992594, 2021). "Likewise, IL-22 facilitates the restitution of epithelium upon inducing acute colonic injury in dextran sulfate sodium (DSS)-induced murine colitis." (PMID 34992594, 2021). "The fuzzy boundary of IL-22 between inhibitor and inducer for colitis may present a dose-/time-dependent manner in the intestine." (PMID 34917080, 2021).
colitis (continued). "Therefore, our studies suggest a need for caution in clinical testing of IL-22 as a therapy for Gut-aGVHD or colitis, especially those patients with potential SR-Gut-aGVHD or colitis." (PMID 33547295, 2021). "Moreover, ILC3s are the primary producer of the cytokine IL22, which is necessary for protecting and recovering the intestine from colitis." (PMID 33513946, 2021). "Furthermore, the AhR has been shown to be an important regulator of T cell immunity in intestinal inflammation, regulating IL-17, Foxp3, IL-10, and IL-22 expression, and altogether ameliorating colitis symptoms and maintaining intestinal homeostasis." (PMID 32366032, 2020). "However, IL-22-expressing ILC3s have been confirmed to be responsible for the development of acute innate colitis in mice." (PMID 33193381, 2020). "IL-22 has been suggested as a critical anti-inflammatory mediator in colitis." (PMID 32957545, 2020). "Therefore, we conclude that C. muridarum alleviates colitis induced by DSS via the IL-22/occludin signal pathway." (PMID 33381598, 2020). "IL-22 exerting a beneficial role in various murine colitis models is well-defined." (PMID 32670290, 2020). "I3C can prevent TNBS-induced colitis in mice primarily through inducing IL-22 production by ILC3s." (PMID 33193381, 2020). "In this regard, ginger ELNs (GELNs) ameliorate mouse colitis via IL-22-dependent mechanisms." (PMID 32486445, 2020). "To address the role of dysbiosis-associated colitis in the immunocompromised host, we used mice lacking IL-22, a cytokine that is important for immune protection at the intestinal barrier." (PMID 33027280, 2020). "Il22−/− mice showed more severe colitis compared with WT control mice." (PMID 32901017, 2020). "Here we show that antibiotic-induced dysbiosis worsened chemically-induced colitis in IL-22-deficient mice, but not in wild-type mice." (PMID 33027280, 2020). "To investigate whether butyrate-induced IL-22 regulates intestinal inflammation upon inflammatory insult, we assessed the role of IL-22 in butyrate inhibition of Dextran sulfate sodium (DSS)-induced colitis." (PMID 32901017, 2020). "Moreover, NKp46-ILC3s drive the transition from colitis to CRC in Helicobacter hepaticus (Hh)+AOM mice and neutralization of IL-22 can ameliorate established colitis and reduce tumor burden." (PMID 33193381, 2020). "The role of IL22 in IBD may need reinterpretation and the rationale for exogenous IL22 supplementation in patients with active colitis may need re-evaluation." (PMID 31792136, 2020). "IL-22 deficient mice exhibit aggravated experimental colitis following DSS exposure, and IL-22 orchestrates epithelial regeneration, proliferation and glycosylation, the production of mucins and anti-bacterial peptides and protects intestinal stem cells from genotoxic stress." (PMID 33193381, 2020). "In fact, the interference with the IL-22/IL-22R pathway exacerbated colitis in some mouse models." (PMID 32906785, 2020). "Also, in DSS-induced colitis, IL-22 has been shown to ameliorate the histological score in an STAT3-dependent manner." (PMID 32670290, 2020). "Indeed, ACT1 expression was elevated to various degrees in colitis mice, whereas IL-22 level was decreased upon arg-1 deletion during colitis." (PMID 32391010, 2020). "Triggering of GPR43 with the SCFAs propionate and acetate (but not butyrate) selectively promoted colonic ILC3 proliferation and expansion and production of IL-22, subsequently protecting mice from chemically induced colitis and from enteric bacterial infection." (PMID 32117267, 2020). "To demonstrate that C. muridarum may alleviate DSS-induced colitis via the IL-22/occludin signaling pathway, we used an anti-IL-22 antibody to determine the specific role of IL-22 and occludin." (PMID 33381598, 2020).
colitis (continued). "The increased sensitivity of NIR readouts for colon permeability is shown using dextran sulfate sodium (DSS) and anti-CD40 murine colitis models in response to interleukin-22 immunoglobulin Fc (IL22Fc) fusion protein and anti-p40 monoclonal antibody treatments, respectively." (PMID 32170183, 2020). "Targeting IL22-regulated pathways and alleviating colonic epithelial ER stress may represent promising therapeutic strategies in patients with colitis." (PMID 31792136, 2020). "In a mouse model of intestinal inflammation (DSS-induced colitis), for example, IL-22 was excessively secreted and the antibody blockade of IL-22 led to exacerbated inflammation in the colon, whereas the IL-22 overexpression resulted in attenuated inflammation." (PMID 30818341, 2019). "The data from these observations emphasize that TP5 increases the expression of IL-22, which may protect mice from colitis." (PMID 31695782, 2019). "Transfer of the CARD9 knockout mouse microbiota to germ-free wild type mice resulted in an exacerbation of colitis, to a similar degree as CARD9 knock out mice – suggesting a causative, rather than correlative, relationship between the microbiome and IL-22 mediated inflammation." (PMID 30850234, 2019). "Therefore, we assumed that enhanced IL-22 expression by these cells contributed to symbiotic-flagellin–mediated intestinal immune homeostasis maintenance in DSS-induced colitis." (PMID 31206517, 2019). "IL-22 is increased in the intestine in patients with IBD as well as murine DSS colitis." (PMID 31816903, 2019). "Exosome-like nanoparticles (ELNs) mdo-miR7267-3p-mediated targeting of Lactobacillus rhamnosus (LGG) monooxygenase ycnE yielded increased indole-3-carboxaldehyde, inducing the production of interleukin (IL)-22 and ameliorating mouse colitis via IL-22-dependent mechanisms." (PMID 31689969, 2019). "Moreover, our data demonstrate that intestinal tissue damage from DSS-induced colitis can be alleviated by supplying exogenous IL-22 or WT macrophages to TREM-1 KO mice." (PMID 31189465, 2019). "In addition, IL-22 antibody administration significantly reduced colorectal inflammation in DSS-induced colitis mice compared with that of control mice." (PMID 31637216, 2019). "Consistently, histologic examination of colonic tissues revealed that activation of AhR with either Ficz or each of the two derivatives led to attenuation of colitis, which was associated with a significant reduction of IFN-γ and TNF-α and up-regulation of IL-22 RNA expression." (PMID 31031628, 2019). "Briefly, the exosomal particles are preferentially engulfed by Lactobacillus rhamnosus and the exosomal microRNAs-cargo target various genes in the bacteria, such as Ginger miR7267-3p that mediate the production of IL-22, favoring an improvement in the colitis via IL-22-dependent mechanisms." (PMID 31921661, 2019). "It is possible that in mice with genetic deficiency of DR3 on ILC3s, constantly suboptimal level of IL-22 from birth makes the individual more susceptible to exacerbated colitis led by lack of IL-22." (PMID 31358760, 2019). "Although much more extensive works still need to fully dissect out the mechanism that determines the beneficial versus deleterious effect of IL-22 on colitis and that stimulates the tumorigenesis pathway, IL-22 activation would be considered to be a promising therapeutic measures for IBD." (PMID 29075900, 2018). "Indeed, like IL-22, the beneficial effect of Ahr activation on experimental colitis has been demonstrated." (PMID 29075900, 2018). "Thus, ATF3 seems to play a more dominant role in the downstream of IL-22 signaling circuit in vivo, compared to a role in IL-6 signaling, as global ATF3−/− mice were more susceptible to DSS colitis and Citrobacter infection." (PMID 30455690, 2018). "However, we should point out that the expression of IL22 is known to be upregulated in the inflamed mucosa, both in CD and in experimental models of colitis." (PMID 30405600, 2018).